CRP (C-reactive protein)
Diseases named in the same sentence as CRP in open-access papers (continued):
Sharing a sentence is not in itself a finding about the gene and the disease.
Sepsis (continued). "In patients with sepsis, the nonspecific CRP biomarker CRP is a more useful tool in predicting improvement and outcome when compared to scoring systems such as the sequential score of organ failure assessment." (PMID 37366985, 2023). "Mean Apo-A1 serum concentrations were significantly lower in dogs with septic shock compared to those with uncomplicated sepsis, while mean CRP and median SAA serum concentrations were not significantly different between groups." (PMID 36937011, 2023). "Several studies found a non-significant difference in CRP levels between vitamin C and placebo teams among sepsis patients." (PMID 38024382, 2023). "suPAR, not CRP, carries the strongest predictive value of the three inflammatory biomarkers (CRP, procalcitonin, and suPAR) in sepsis patients." (PMID 36766787, 2023). "Procalcitonin (PCT) and C-reactive protein (CRP) are commonly used as markers to diagnose sepsis and septic shock; however, both of these, as well as the neutrophil marker CD64, currently have limited specificity and sensitivity as sepsis biomarkers." (PMID 38343439, 2023). "In addition, the sepsis group showed significantly higher levels of white blood cell count (WBC), percentage of neutrophils (N %), PCT, and CRP levels than the control group (P < 0.05)." (PMID 36690951, 2023). "In addition, presepsin levels rise earlier than CRP or PCT in response to sepsis, which indicated their potential values as biomarkers for early diagnosis of sepsis." (PMID 37147598, 2023). "Similarly, in our study, we found a positive correlation between YKL-40 levels and CRP, WBC, and ANC, biomarkers that are usually elevated in sepsis." (PMID 37238320, 2023). "Despite these findings, our reverse analysis did not indicate any influence of sepsis on the gut microbiota and CRP levels." (PMID 37662942, 2023). "In addition, existing laboratory parameters such as CRP, PCT, and WBC counts have limited specificity and sensitivity for evaluating sepsis in children." (PMID 38029254, 2023). "Among the sepsis biomarkers, NE-SFL/NE-WY were strongly associated with PCT and IL-6, but not with presepsin or CRP." (PMID 37324133, 2023). "The reason for not including additional parameters in the analysis is, by suggestion of clinical experts, that PCT should be considered an addition to the SoC for patients with suspected sepsis in Belgium, as PCT adds value over the use of C-reactive protein tests." (PMID 37903106, 2023). "Compared with those who developed sepsis-induced AF, patients who did not have AF showed a lower CRP level." (PMID 36793274, 2023). "PCT and CRP have also been well-documented for their use in sepsis and in discriminating between infectious and non-infectious etiology." (PMID 37626646, 2023). "Septic patients showed increased levels of CRP (septic patients: 182.9 ± 132.9 mg/mL; non-septic patients: 93.46 ± 117.6 mg/mL; p = 0.030) and sepsis index (septic patients: 0.19 ± 0.19; non-septic patients: 0.08 ± 0.08; p = 0.010) on day +3 after admission." (PMID 37509475, 2023). "While markers such as CRP and I/T ratio have been shown independently to have high sensitivities, these findings depend on timing from the onset of sepsis, either lacking accuracy early on or losing accuracy later in the course of sepsis." (PMID 38012554, 2023). "In summary, neither CRP nor PCT is an ideal laboratory indicator for the early diagnosis of sepsis in VLBW infants." (PMID 37139640, 2023). "This suggests that initial CRP values do not reflect the prognosis of patients with sepsis in the ICU." (PMID 37709919, 2023). "For example, if CRP and ESR are correlated and show similar missingness in a study investigating a time-sensitive aspect of sepsis, keeping CRP and removing ESR would make more sense since CRP is a more sensitive indicator of rapid inflammatory response than ESR." (PMID 36793336, 2023).
Sepsis (continued). "Therefore, procalcitonin testing is preserved as an auxiliary test for patients with ambiguous diagnoses of sepsis or bacterial infection, which cannot be verified on the basis of the WBC count, NLR, or CRP level." (PMID 36977993, 2023). "The pathophysiological basis is still not completely clear, and it is difficult to diagnose or distinguish from sepsis in the early stages and current infection makers such as C-reactive protein (CRP) and procalcitonin are not specific." (PMID 36806964, 2023). "However, research regarding the acute phase response in malnourished infants with sepsis has focused mainly on PCT and CRP." (PMID 37892278, 2023). "The AUCs for PCT, ALB and CRP were 0.69 (95% CI, 0.66–0.73, p < 0.001), 0.68 (95% CI, 0.65–0.72, p < 0.001) and 0.68 (95% CI, 0.64–0.71, p < 0.001), respectively, which were lower than the AUC for PAR in predicting sepsis in neonates with pneumonia (p < 0.05)." (PMID 36908271, 2023). "In this study, we aimed to focus on patients with suspected sepsis in the emergency department (ED) and compare the performances of p-calprotectin, PCT, CRP, and NLR in predicting the need for direct transfer to the ICU or HDU as decided by a multidisciplinary team." (PMID 36774492, 2023). "Except in one report, all prior investigations found significantly higher levels of salivary CRP in neonates with sepsis than those without sepsis." (PMID 36900011, 2023). "Baseline, isolated measurement of PCT, CRP, IL-6, and sCD14 has not been shown to help predict mortality in critically ill patients with sepsis." (PMID 37537680, 2023). "The logistic regression results in our study revealed that PCT, CRP, and CREA were not independent risk factors for sepsis (p>0.05), consistent with the findings of numerous studies." (PMID 36189371, 2022). "In patients with severe sepsis, the levels of CK-18 and PCT on d1, and the level of CRP both on d1 and d2, were higher than in patients without severe sepsis." (PMID 34255216, 2022). "In contrast, most infection/inflammatory biomarkers (e.g., C-reactive protein, leukocytes, interlukin-6) are elevated in many non-viral illnesses (e.g., trauma, sepsis)." (PMID 36685600, 2022). "CRP's normal serial value is a reliable indicator of the absence of infant sepsis and can be used to identify when medicines should be stopped." (PMID 35449688, 2022). "Single values of CRP or procalcitonin are neither sensitive nor specific to guide care decisions in the diagnosis of sepsis." (PMID 35874568, 2022). "The biomarkers such as CRP and PCT can also guide to initiate antibiotics while waiting for PCR results and they have been widely investigated in the differential diagnosis of community-acquired pneumonia and sepsis, previously." (PMID 34493032, 2022). "Out of 148 newborns with clinical signs of sepsis, 108 (72.9%) had positive CRP 2 results (>5mg/L), while 40 (27.0%) had negative CRP 2 results (5mg/L)." (PMID 37654832, 2022). "In sepsis patients with and without bacteraemia the median admission values of CRP were 196.0 and 150.0 mg/L, respectively, with corresponding PCT levels 43.0 versus 10.0 μg/L, and WBC 11.0 versus 16.7 × 109/L." (PMID 36050405, 2022). "Out of 148 neonates with clinical symptoms of sepsis, 97 (65.54%) neonates had CRP 1 that was positive (>5mg/L), while 51 (34.45%) of those same neonates had negative CRP (5mg/L)." (PMID 37654832, 2022). "So, we suggest, for obtaining the best results, CRP be combined with other markers and not used alone as a sepsis marker." (PMID 36158418, 2022). "Within six hours of the start of an infectious process, the liver begins to manufacture C-reactive protein, an acute-phase reactant protein.A single CRP measurement within 6 hours of clinical suspicion of sepsis is insufficient to diagnose neonatal septicemia." (PMID 37654832, 2022). "CRP, PCT and also IL-6, IL-8 and sFAS levels were significantly higher in patients with sepsis." (PMID 35550043, 2022).
Sepsis (continued). "The AUC for CRP, ALB, and PCT was 0.67 (95% CI 0.64-0.71, P < 0.001), 0.70 (95% CI 0.66-0.74, P < 0.001), and 0.70 (95% CI 0.66-0.79, P < 0.001), which were lower than the AUC for CAR in predicting sepsis in neonates with pneumonia (P < 0.05)." (PMID 35873709, 2022). "⁠CRP has shown to have fair sensitivity of 75%, specificity of 67% and area under the curve (AUC) of 0.77 for distinguishing patients with sepsis from non-infectious SIRS." (PMID 35550043, 2022). "In the early years, erythrocyte sedimentation rate (ESR) and CRP as markers of inflammation were used in diagnosis of sepsis, however, these markers have limitations due to lack of specificity for sepsis." (PMID 35149759, 2022). "Some clinical markers, such as procalcitonin (PCT) and C-reactive protein (CRP), have predictive value for septic prognosis, but their specificity or sensitivity are significantly limited by the clinical and pathogenetic heterogeneities of sepsis." (PMID 35592322, 2022). "Participants with consolidation did not differed from those without in terms of C-reactive protein – 245 mg/l versus 271 mg/l, P-value 0.58 – and procalcitonin – 10 ng/ml versus 11 ng/ml, P-value 0.47 –, laboratory tests suggestive of sepsis." (PMID 35227201, 2022). "For example, long non-coding metastasis-associated lung adenocarcinoma transcript 1 (lnc-MALAT1) and micro RNA (miR)-125a were increased in sepsis patients compared with healthy controls and positively correlated with APACHE-II score, SOFA score, serum creatinine, CRP, TNF-α, IL-1β, IL-6, and IL-8." (PMID 34991675, 2022). "FTB treatment lowered the levels of CRP, IL-6, IL-1β, and TNF-α in rats with sepsis." (PMID 36408247, 2022). "Sensitivity, specificity, PPV, NPV of CRP1 and CRP2,WBC 1and WBC 2 were compared withculture positive and negative sepsis.CRP 2 showed high sensitivity 96% and high NPV95% with significant p value <0.0001." (PMID 37654832, 2022). "Regarding miR-199a-3p, it was found to be significantly positively correlated with birth weight, Apgar score at 1 min, weight, and platelet count, while it was negatively correlated with each of respiratory rate, heart rate, TLC, RDW, RBS,CRP, as well as SNAPII in neonates with sepsis." (PMID 34990478, 2022). "CRP and PCT were significantly higher in the sepsis group than in the SIRS group." (PMID 36475186, 2022). "The optimal cut-off value of the CRP level to discriminate between sepsis and non-infectious organ failure was 3.53 mg/L (sensitivity, 77.0%; specificity, 85.2%; AUC, 0.858; 95% CI 0.821–0.890; p < 0.001)." (PMID 34983420, 2022). "The meta-analysis on the predictive value of PCT for sepsis demonstrated that PCT was a useful laboratory indicator for early prediction of sepsis, and PCT had higher specificity and accuracy compared with CRP." (PMID 36214882, 2022). "In our patient group, patients with sepsis had significantly higher levels of CRP that patients without sepsis; at a cut-off level of 69.9 mg/L it had a sensitivity of 82% and specificity of 64% in predicting sepsis." (PMID 35550043, 2022). "C-reactive protein (CRP), procalcitonin (PCT), and presepsin are practical to be used in daily clinical practice and were evaluated in patients with different stages of LC as the markers of infections or sepsis." (PMID 36140479, 2022). "However, some acute phase reactants and inflammatory mediators are predictors of sepsis, such as procalcitonin (PCT), interleukins 6 and 8, C-reactive protein (CRP), and fibrinogen." (PMID 36553264, 2022). "Several studies compared the CRP levels in ICU survivors vs. non-survivors with sepsis without finding any differences." (PMID 35907785, 2022). "In this study, we found that C-reactive protein and NLR were increased in the sepsis and prolonged hospital stays group, thus indicating that C-reactive protein and NLR may play essential roles in the prognosis of PLA." (PMID 35864446, 2022).
Sepsis (continued). "Among surgical patients in need of intensive care, the performance of plasma sDLL1 concentration was not superior to CRP but superior to leukocyte count regarding the prediction of sepsis." (PMID 35922468, 2022). "Other common biomarkers of infection and potential sepsis were recorded, including first WBC count (mean: 10.0 ± 4.5, median: 9.25), first ESR (mean: 22.7 ± 26.2, median: 13.0), first CRP (mean: 4.9 ± 7.4, median: 1.0), and first procalcitonin level (mean: 0.9 ± 3.5, median: 1.0)." (PMID 36185926, 2022). "CRP is a specific, although late, biomarker for infant infection detection and normal levels indicate that sepsis is not present, and antibiotic treatment should be discontinued." (PMID 35449688, 2022). "Our study has shown that chemerin performed similarly to CRP and better than other biomarkers for the early discrimination of sepsis severity, while chemerin at enrollment, but not CRP, predicted 28-day mortality independently of the APACHE II score." (PMID 35204801, 2022). "Second, the predictive value of sDLL1 for the detection of sepsis was sufficient, but it did not perform superiorly to CRP." (PMID 35922468, 2022). "To date, most clinicians utilize CRP and PCT to predict sepsis in the ED." (PMID 34983430, 2022). "The most used nonspecific biomarker is CRP, but the specificity is low, and it is not possible to differentiate NEC with sepsis, or other causes of inflammation, based on CRP alone." (PMID 36518779, 2022). "Neonatal sepsis was defined as either culture-proven sepsis (positive blood culture) or clinical sepsis (at least one symptom and elevated C-reactive protein (CRP) concentrations within 72 h with negative blood culture)." (PMID 36233706, 2022). "On follow up after 48 h of antibiotic treatment, CRP was higher in BCxS and CS than in rule out sepsis." (PMID 35820876, 2022). "We used various combinations of CRP, PCT, sepsis, and postoperative period to search all databases." (PMID 36475186, 2022). "This would explain why increased tacrolimus exposure is not observed in transplant patients with comparable CRP levels for, e.g., septicaemia, where IL-6 or other inflammatory mediators are not expected to be elevated." (PMID 35651879, 2022). "In the first population in our study, a high percentage of newborns (63% of treated infants) received prolonged antibiotic courses due to elevated values of CRP, but sepsis was ruled out in 98.8% of them." (PMID 36009958, 2022). "Presepsin, PCT, and CRP levels were significantly higher in patients with sepsis or septic shock than in those with non-infectious organ failure." (PMID 34983420, 2022). "WBC count, neutrophil classification and CRP elevation are not specific to septicemia, so scholars at home and abroad are committed to exploring more sensitive indicators for early diagnosis." (PMID 35633256, 2022). "Although procalcitonin (PCT) and C-reactive protein (CRP) are the most frequently used in clinical practice, the most recent Surviving Sepsis Campaign guidelines for the management of sepsis mention that sepsis biomarkers, specifically PCT, are not superior to clinical evaluation." (PMID 36359365, 2022). "The classification of cases as requiring antimicrobial treatment due to sepsis or not requiring antimicrobial treatment did not influence the CRP values based on the defined criteria of this study." (PMID 36713872, 2022). "It has proven valuable in high-income settings, where one single CRP value between 8 h and 36 h from admission had a negative predictive value for sepsis of >99%." (PMID 35622691, 2022). "Our results are novel with respect to combined use of CRP, PCT, nCD64 index as markers of sepsis." (PMID 35907785, 2022). "CRP and PCT, cheap and readily available, are by far the most routinely used biomarkers for sepsis." (PMID 35907785, 2022). "L-lactate, CRP, and procalcitonin (PCT) are serving as specific biomarkers in sepsis." (PMID 35463634, 2022).
Sepsis (continued). "This study revealed that the mtDNA copy number was significantly higher in non-survivors than in survivors among critically ill patients with sepsis, although no intergroup differences were noted in CRP and lactate levels." (PMID 36289650, 2022). "However, currently, C-reactive protein (CRP), calcitonin (PCT), and other inflammatory markers are more widely used for the diagnosis of sepsis and the prediction of its progression." (PMID 35676730, 2022). "Finally, we found a significant correlation between the SChE activity and other biomarkers of sepsis on ICU admission—in particular, with CRP (P = 0.02; r = –0.2), leukocytes (P = 0.002; r = –0.27), and procalcitonin (P = 0.03; r = –0.20)." (PMID 35895337, 2022). "collected statistics of complete blood count, C-reactive protein (CRP), IL-6, levels of cell-free DNA (cfDNA), neutrophil elastase (NE) and myeloperoxidase (MPO) in umbilical cord blood to try to predict the early-onset sepsis." (PMID 35572571, 2022). "CRP levels were explored by tumour site as well as presence of sepsis and these did not explain the difference between HW-CO2 and DC-CO2 groups." (PMID 35794366, 2022). "Lactate levels were associated with SAPS-3 at admission in both sepsis and non-sepsis patients, in contrast to HBP, CRP, PCT, and WBC levels." (PMID 36050405, 2022). "In addition, sepsis patients had higher SOFA scores in the discovery cohort, creatinine, CRP, lactate and SOFA scores in the training cohort, and creatinine and lactate in the test and cohorts (P < 0.05)." (PMID 35663956, 2022). "AUC, sensitivity, and specificity of MDW, CRP and PCT for the assessment of sepsis." (PMID 36538555, 2022). "PCT appears to be a superior prognostic marker for general sepsis when compared to C-reactive protein (CRP), which has not yet been explicitly studied in urosepsis." (PMID 35732880, 2022). "These variables included serum C-reactive protein, PCT levels, and some other inflammation-related biomarkers, which may be helpful for researchers to elucidate the mechanism of sepsis mortality." (PMID 36407534, 2022). "ascertained that patients who developed sepsis-driven AF had a higher CRP compared to those who did not (P < 0.0001) intimating a close relationship between sepsis, inflammation and AF." (PMID 34763982, 2022). "It is also fundamental to underline the good performances of the biomarkers in the survival analysis, considering that the most common biomarkers for sepsis evaluation (CRP, PCT) failed to be good predictors of adverse events in our study." (PMID 36556987, 2022). "Furthermore, lnc‐GAS5 was negatively related to CRP (p = 0.002) and APACHE II score (p = 0.004) in sepsis patients." (PMID 35325494, 2022). "By evaluating the value of PCT, CRP, and NLR in assessing the condition of patients with sepsis due to bloodstream infection, it was found that the levels of NLR, CRP, and PCT were significantly higher in patients with sepsis due to severe bloodstream infection than in the non-severe group." (PMID 35345421, 2022). "From an antibiotic stewardship perspective, using CRP in this case is not useful to rule in or rule out infection in most cases of early-onset sepsis." (PMID 36611468, 2022). "In previous studies, CRP, IL6, and lactate could be used as biomarkers to evaluate the diagnosis and prognosis of sepsis severity in humans." (PMID 35205254, 2022). "Outcome measures will consist of changes in C-reactive protein (CRP), a putative marker of sepsis at 72 hours (continuous) and microbiological cure (seven-day) (binary), alone and as a composite with seven-day survival, while providing preliminary data on longer-term survival (to day 90)." (PMID 37519413, 2021). "Sex and disease severity were not significant covariates in longitudinal changes of CRP post-sepsis (data not shown)." (PMID 34869619, 2021). "The cut-off values of CRP level were 59.45 mg/L and 57.50 mg/L for infected without sepsis and sepsis, respectively." (PMID 34344141, 2021).